HMGB1 (high mobility group box 1)
Diseases named in the same sentence as HMGB1 in open-access papers (continued):
Sharing a sentence is not in itself a finding about the gene and the disease.
Sepsis (continued). "However, there have been no direct reports indicating that the removal of IL-6 or HMGB-1 improved sepsis mortality." (PMID 36005726, 2022). "In sepsis mice model induced by CLP, the expression levels of miR-129-5p and HMGB1 were measured by quantitative real-time polymerase chain reaction and western blot, and the correlation between miR-129-5p and HMGB1 was verified by luciferase assay and RNA immunoprecipitation." (PMID 35720285, 2022). "In addition, HMGB1 expression was found to be increased in septic acute kidney injury (AKI) mouse models, and serum HMGB1 levels were positively correlated with the severity of sepsis." (PMID 36081910, 2022). "Therefore, HMGB1 should be evaluated as a late‐stage prognostic factor or as a marker of the therapeutic response, rather than an early marker of sepsis." (PMID 33140586, 2021). "Numerous animal studies have revealed that HMGB1 is a negative outcome predictor of sepsis." (PMID 34743181, 2021). "Nevertheless, the source of extracellular release of HMGB1 is not yet clearly confirmed in sepsis." (PMID 33947887, 2021). "Thus, we did not expect high levels of HMGB1, such as observed in high aseptic inflammation of exercise or in sepsis." (PMID 34198762, 2021). "However, the researchers did not obtain positive results because HMGB1 was not better than procalcitonin in identifying severe sepsis." (PMID 33140586, 2021). "However, the specific details of the activation of the NF-κB pathway by the HMGB1-RAGE axis are not yet clear in sepsis." (PMID 33552058, 2020). "Also, acupuncture therapies were reported as being capable of decreasing secretion of IL-6, high mobility group protein box-1 (HMGB1), TNF-α, IL-10, and interferon-γ (IFN-γ), demonstrating acupuncture at ST36's potential of reducing inflammation in sepsis." (PMID 32215037, 2020). "Consequently, HMGB1 not only augments the PAMP/DAMP-induced inflammation, but also promotes the PAMP/DAMP-induced pyroptosis, leading to dysregulated inflammatory responses as well as macrophage depletion and possible immunosuppression during sepsis." (PMID 32265930, 2020). "Several mechanisms of the release of exosomal HMGB1 from cells have been revealed so far, such as the activation of TLR4 and caspase-11/gasdermin D (GSDMD) signaling, decreased autophagy and endoplasmic reticulum (ER) stress, all of which are important cellular mechanisms of sepsis pathophysiology." (PMID 33013905, 2020). "Therefore, it is expected that HMGB1 will be a prognostic biomarker of sepsis and other non-infectious systemic inflammatory conditions." (PMID 32635454, 2020). "The HMGB1 levels were unchanged in survivors and non-survivors regardless of sepsis complication." (PMID 32635454, 2020). "Biomarkers which do not clearly distinguish between survivors and nonsurvivors at onset of sepsis (HMGB1 and sTREM-1) could still provide important prognostic information when assessed at a further time point." (PMID 31705327, 2019). "Hsp70 and HMGB1 are classical DAMPs and have been extensively investigated, whereas the inflammation-inducing DAMP property of extracellular CIRBP is a recent observation that has been shown to perpetuate the inflammatory response in hemorrhagic shock and sepsis patients." (PMID 31293389, 2019). "Similarly, HMGB1 levels in other systemic inflammatory disorders, such as acute respiratory distress syndrome or sepsis, at disease onset did not predict survival." (PMID 29795561, 2018). "However, the expression and the potential role of HMGB1 in different brain regions and during early phase of sepsis have not been elucidated yet." (PMID 29190939, 2017). "In sepsis, C5aR2, not C5aR1, was responsible for the release of HMGB1, which was supported by an observation made by Croker and colleagues that high mobility group bow-1 (HMGB1) production from macrophages was independent on C5aR1-C5aR2 heteromer." (PMID 28706957, 2017).
Sepsis (continued). "HMGB1, a nonhistone nuclear protein, is released from nuclei into extracellular milieu, and acts as a cytokine-like mediator in many inflammatory diseases, such as sepsis, rheumatoid arthritis." (PMID 27026909, 2016). "In vitro, compound 121 not only inhibited the release of HMGB1, the production of inducible nitric oxide synthase and NO, but also induced HO-1 expression in a concentration-dependent manner; in vivo, it increased survival and decreased the HMGB1 levels of serum and lung in CLP-induced sepsis." (PMID 27483229, 2016). "In addition to inflammatory cytokines, other factors have recently been shown to mediate the lethal late phase of sepsis; these factors include tumor necrosis factor (TNF)-α, IL-1, high-mobility group box-1 (HMGB1) protein, and nuclear architectural chromatin-binding protein." (PMID 27011792, 2016). "We observed that the increase in HMGB-1 levels began later in our model compared to production kinetics observed in in vitro stimulation assays, However, kinetics of our model were consistent with the delayed contribution HMGB-1 is proposed to have during sepsis." (PMID 27556404, 2016). "In addition, anti-HMGB1antibodies prevented death in experimental mice with sepsis and the resultant ALI,indicating that therapeutic agents that attenuate HMGB1 release may have potential forthe prevention and treatment of ALI." (PMID 26648090, 2016). "Interestingly, HMGB-1, a cytokine with a negative predictive value on survival in sepsis, was indeed significantly increased in propofol + CLP rats, that is, in the animals that actually succumbed earlier as compared to isoflurane + CLP animals." (PMID 25887642, 2015). "However, the role of HMGB1 regarding vascular reactivity has not been clarified, especially during the early phase of sepsis." (PMID 23532259, 2013). "Unlike other pro-inflammatory cytokines, HMGB1 is a late appearing inflammatory cytokine and might become a unique target for treatment in sepsis, since it provides a sufficient time frame for clinical intervention against progressive inflammatory disorders." (PMID 23497622, 2013). "However, administration of a monoclonal anti-HMGB1 antibody (2G7), given prophylactically at a dose previously shown to confer protection in experimental sepsis models, did not improve survival or modulate peripheral levels of key inflammatory markers." (PMID 23506269, 2013). "Herein, we did not further explore the well described anti-inflammatory effects of dexmedetomidine (beyond HMGB1 levels); however, dexmedetomidine reduces systemic levels of IL-6 and TNF-α following lipopolysaccharide infusion in rats and following cardiac surgery and sepsis in humans." (PMID 21702944, 2011). "While HMGB1 is known to be released actively by innate immune cells (monocytes-macrophages) stimulated by numerous inflammatory mediators (including cytokines) and passively by necrotic cells, it is not yet clear where histones come from during sepsis." (PMID 21415977, 2010). "However, whilst some reports demonstrate that monoclonal anti-HMGB1 antibodies are efficacious preventing organ damage in experimental models of sepsis, others suggest that monoclonal antibodies are not effective in suppressing arthritic disease in vivo." (PMID 20706656, 2010). "In light of the late and prolonged kinetics of HMGB1 accumulation in experimental sepsis, we reasoned that it might be possible to rescue mice from lethal sepsis even if EGCG is administered after the onset of sepsis." (PMID 17987129, 2007). "Consequently, delayed administration of EGCG did not affect circulating levels of TNF at late stage of sepsis, but specifically attenuated systemic accumulation of HMGB1, as well as IL-6 and KC-two most reliable surrogate markers of lethal sepsis." (PMID 17987129, 2007). "In contrast to HMGB1, IL-6 and KC may not critically important in the pathogenesis of sepsis, because neither anti-IL-6 nor anti-KC antibodies confer long-lasting protection against lethal sepsis." (PMID 17987129, 2007).
Sepsis (continued). "Although delayed administration of EGCG did not attenuate circulating TNF levels at 52 h after the onset of sepsis, it did significantly attenuate circulating levels of HMGB1 (P<0.05), suggesting that EGCG confers protection against lethal sepsis partly by attenuating systemic HMGB1 accumulation." (PMID 17987129, 2007). "In sepsis, the most common effect of GSDMs proteins is to induce pyroptosis, which leads to cellular rupture and non-specific release of cellular components, such as HMGB1 and pro-inflammatory cytokines such as IL-1, IL-18 and TNF-α, ultimately triggering inflammatory responses." (PMID 38022612, 2023). "However, during sepsis, the reduction of oxidized HMGB1 by thioredoxin is not efficient." (PMID 38020710, 2023). "The role of HMGB1 in sepsis pathogenesis has already been outlined by several studies stating that levels of HMGB1 are elevated in non-survivors, in patients with more severe organ failure and DIC; targeting HMGB1 may improve outcomes in sepsis experimental models." (PMID 36675530, 2023). "Similarly, GLY (pH not specified) protected rats against sepsis by inhibiting HMGB1 signaling." (PMID 35127554, 2021). "Further investigations in the HMGB1-RAGE-TLR4/TLR2 axis in platelet activation using recombinant HMGB1 or platelet-derived HMGB1 and knockouts will be warranted in dogs considering that RAGE-dependent mechanisms may be central to the pathogenesis of thrombosis in sepsis." (PMID 34235204, 2021). "As HMGB1, which is secreted from immune and dying cells during cellular infection and injury, is a major promoter of inflammation, the peptide blocking HMGB1/RAGE interaction could become a useful therapeutic against HMGB1/RAGE-mediated sepsis and other inflammatory diseases." (PMID 33562633, 2021). "After the activation of TLR, HMGB1 could acetylate and trigger its translocation from the nucleus to the circulation and interact with a variety of target cell receptors (RAGE, TLR2, TLR4, etc.), stimulating the release of pro-inflammatory cyto-/chemokines and leading to inflammations and sepsis." (PMID 34938184, 2021). "However, the mechanism of HMGB1 release of hepatocytes during sepsis is not very clear." (PMID 32328059, 2020). "Chronic inflammation may lead to several inflammatory disorders including sepsis, rheumatoid arthritis, asthma, diabetes and Crohn’s disease and involves production and secretion of various pro-inflammatory cytokines including IL6, TNF and high mobility group box-1 (HMGB1)." (PMID 30947238, 2019). "If HMGB1 is considered a strong pro-inflammatory cytokine involved in the pro-inflammatory phase of SIRS/sepsis, it could be hypothesised that lower levels could be observed when the patient with severe sepsis/septic shock moves from a pro-inflammatory state to a state with immune paresis." (PMID 17346334, 2007). "High mobility group box 1 (HMGB1) is a non-histone DNA binding protein, which can be released into extracellular environment and as a late mediator of endotoxin lethality in sepsis." (PMID 39372401, 2024). "In a cross-sectional study enrolling patients without sepsis, serum S100A12 and HMGB1 levels were elevated in patients with AKI compared to those in patients on hemodialysis." (PMID 36143874, 2022). "A chromatin-binding non-histone protein, high mobility group box 1 (HMGB1), is released from the nucleus to the extracellular milieu in particular environments such as autoimmunity, sepsis and hypoxia." (PMID 33807604, 2021). "Nicotine, a non-selective α7nAChR agonist, inhibits HMGB1 release from LPS-stimulated macrophages and increases the survival of animals in a cecal ligation and puncture (CLP) model of sepsis." (PMID 33126860, 2020). "HMGB1 is considered as a late mediator compared with the release of other cytokines, such as TNF and IL-1, in response to lethality during sepsis as well as after necrosis, but not apoptosis or death." (PMID 29440779, 2017).
Sepsis (continued). "The main aim of this study was to compare the levels of HMGB1, LBP, IL-6 and CRP between infected children without systemic inflammatory response syndrome (SIRS) and children with sepsis of different severity levels." (PMID 20158885, 2010). "Levels of HMGB1, LBP, IL-6 and CRP in infected children without SIRS, with sepsis and with severe sepsis." (PMID 20158885, 2010). "Levels of HMGB1 were significantly higher in infected patients (infection without SIRS, sepsis, and severe sepsis) without bacteraemia (n = 94) and in patients with bacteraemia (n = 12) compared to healthy controls." (PMID 17346334, 2007). "Notably, a recent single-institution study, including 218 critically ill patients (145 with sepsis and 73 without sepsis), revealed that blood HMGB1 levels positively correlated with blood lactate levels (r = 0.144, P = 0.035), suggesting that lactate could regulate HMGB1 release in sepsis." (PMID 34363018, 2022). "The plasma levels of AGE, HMGB1, and S100A12 did not change in patients with sepsis after 6 d." (PMID 35723375, 2022). "However, our study showed that HMGB1 levels were not different between survivors and non-survivors and were unchanged through 6 h post ICU admission among patients with and without sepsis." (PMID 32635454, 2020). "In vitro a significant reduction for IL-6, IFN-y, MIP-1α, C5a, HMGB-1, procalcitonin and S100-A8, but not of TNF-α could be achieved in blood samples with sepsis-like high cytokine levels by binding to CytoSorb® hemoadsorbent polystyrene beads." (PMID 33141843, 2020). "Sepsis-induced AKI in mice with chronic kidney disease (CKD) increased the expression of vascular endothelial growth factor (VEGF) and HMGB1 levels; however, inhibition of HMGB1, but not VEGF, was found to be protective." (PMID 32974364, 2020). "Hydrogen treatment was recently associated with down-regulation of the expression of HMGB1 and pro-inflammatory cytokines during sepsis and myocardial IRI, but it is not known whether hydrogen has an effect on HMGB1 in liver IRI." (PMID 24410860, 2014). "In light of our observation that administration of fetuin-A markedly reduced circulating levels of HMGB1, but not TNF-α (data not shown), we propose that fetuin-A confers protection against lethal endotoxemia and sepsis partly by inhibiting late mediators of these diseases." (PMID 21347455, 2011). "Furthermore, we did not found a significant difference between HMGB1 levels in infected patients without SIRS and patients with sepsis." (PMID 20158885, 2010). "In the current study, anti-HMGB1 treatment did not affect circulating levels of inflammatory cytokines induced by PbA infection, although the same antibody has been shown to attenuate levels of inflammatory cytokines induced by CLP in an experimental sepsis model." (PMID 23506269, 2013).
breast carcinoma (214 papers, 2010 to 2026). "HMGB1 is positively associated with autophagy levels, NFκB/P65 activity, and doxorubicin resistance in breast cancer cells, with its role in promoting resistance attributed to its ability to trigger autophagy." (PMID 40723786, 2025). "HMGB1 is reportedly associated with radioresistance in esophageal squamous cell carcinoma and breast cancer." (PMID 41164196, 2025). "Cancer-associated fibroblasts (CAFs) in breast cancer have been shown to induce HMGB1 expression in cancer cells and contribute to the pool of extracellular HMGB1 following chemotherapy." (PMID 41465435, 2025). "From a clinical perspective, interfering with the functions of HMGB1 renders breast cancer patients with TLR4 allele loss more susceptible to relapse after treatment." (PMID 39916954, 2024). "The genetic predisposition of polymorphism in HMGB1 genes to breast cancer prognosis was evaluated by four studies." (PMID 39830522, 2024). "In the present study, HMGB1 treatment of breast cancer cells with intact or deficient RAGE expression revealed the ligation of HMGB1-RAGE through PI3K/AKT signaling pathways leading to cancer cell migration and invasion." (PMID 35610613, 2022). "Potential substances secreted by breast cancer associated fibroblasts (BCFs) will induce intracellular HMGB1 expression in breast cancer cells." (PMID 35340325, 2022). "HMGB1 is systemically elevated in CAFs from luminal breast cancer, and thus has been associated with resistance to endocrine therapy." (PMID 34182538, 2021). "Based on data provided by bioinformatic analysis and the fact that the expression of HMGB1 is associated with that of GPR30 in breast cancer tissues, we verified the interaction between these two molecules." (PMID 34182538, 2021). "The hypoxic tumor environment is known to regulate HMGB1 secretion, but an understanding of the underlying mechanism by which tumor-derived HMGB1 regulates interstitial components and promotes breast cancer lung metastasis has remained elusive." (PMID 32943604, 2020). "High mobility group box 1 (HMGB1) is reported to be associated with the radioresistance in bladder and breast cancer." (PMID 30755598, 2019). "In the case of HMGB1, changes in the levels of circulating HMGB1 have been associated with the response to neoadjuvant therapy in breast cancer patients." (PMID 31779212, 2019). "Recent studies have reported that HMGB1 polymorphism is associated with susceptibility to several carcinomas including breast cancer, melanoma, gastric cancer and colorectal cancer." (PMID 28423715, 2017). "DOX resistance in breast cancer cells was shown to be associated with fibroblast-induced high mobility group box 1 (HMGB1) expression." (PMID 27391808, 2016). "It will be very intriguing to know how the components of HMGB1/RAGE pathway alter genetic susceptibility to breast cancer." (PMID 27241711, 2016). "Tumor necrosis has been associated with a poor outcome in breast carcinoma and usually generates cytokine-like IL-1 and HMGB1 with a role of promoting inflammatory response and neoangiogenesis." (PMID 26884644, 2016). "To enrich our knowledge in understanding the genetic basis of breast cancer, we in this study focused on the components of HMGB1/RAGE pathway to evaluate their genetic predisposition to the development of breast cancer in Chinese." (PMID 27241711, 2016). "Our findings altogether demonstrate a significant association between RAGE gene rs1800624 polymorphism and breast cancer risk, and more importantly a cumulative impact of multiple risk associated polymorphisms in HMGB1/RAGE pathway on breast carcinogenesis." (PMID 27241711, 2016). "This study aimed to explore the effect of secreted substances from breast cancer-associated fibroblasts (BCFs) on HMGB1 expression in breast cancer cells and the potential of extracellular HMGB1 to influence chemosensitivity." (PMID 25512109, 2014).